NBPF1 (NBPF member 1)
Diseases named in the same sentence as NBPF1 in open-access papers:
NBPF1 is named in the same sentence as 24 diseases in open-access papers, as found by Europe PMC text mining. Sharing a sentence is not in itself a finding about the gene and the disease. The quoted sentences say what the papers report.
neuroblastoma (13 papers, 2008 to 2025). Neuroblastoma (NB) is the most common solid, extracranial childhood tumor. "NBPF1 (Neuroblastoma Breakpoint Family, member 1) is a tumor suppressor gene associated with several cancers, including gastric cancer and neuroblastoma." (PMID 37454130, 2023). "The expression pattern of NBPF1 is reminiscent of the expression analysis of other genes located in the 1p35-36 region, where 15–20% of the genes showed a lower expression level in neuroblastoma tumors and cell lines with 1p loss of heterozygosity." (PMID 18493581, 2008). "Decreased expression of NBPF1 in neuroblastoma cell lines with loss of 1p36 heterozygosity and the marked decrease of anchorage-independent clonal growth of DLD1 colorectal carcinoma cells with induced NBPF1 expression further suggest that NBPF1 functions as tumor suppressor." (PMID 25958384, 2015). "Expression studies in neuroblastoma and colon cancer showed that cancer cell decreases in clonal expansion were linked to the NBPF, suggesting that NBPF1 can act as tumour suppressor." (PMID 40564862, 2025). "On the one hand, the tumor suppressive function of NBPF1 has been observed in prostate cancer, neuroblastoma, cutaneous squamous cell carcinoma and cervical cancer." (PMID 37296706, 2023). "On the one hand, the tumor-suppressing functions of NBPF1 have been definitively observed in neuroblastoma, prostate cancer, cutaneous squamous cell carcinoma, and cervical cancer." (PMID 36060966, 2022). "A meta-analysis based on the Oncomine database showed that levels of NBPF1 were decreased in neuroblastomas that recurred within five years." (PMID 36060966, 2022). "This large gene family received the nomenclature of NBPF genes because one of its members (NBPF1) was found to be disrupted by a chromosomal translocation in a neuroblastoma patient." (PMID 34650102, 2021). "Two CDK family genes, CDK11A and CDK11B, are known to play multiple roles in cell cycle progression, cytokinesis and apoptosis, while the gene NBPF1 acts as a tumor suppressor by arresting cell cycle at G1 stage in Neuroblastoma." (PMID 29621297, 2018). "The segment, which is classified as amplified, maps to the neuroblastoma breakpoint family gene NBPF14, so-called because NBPF1 (1p36.13) was discovered in a screen for genes disrupted by a translocation in a neuroblastoma brain cancer patient's normal genome." (PMID 30397684, 2018). "NBPF1 belongs to the neuroblastoma breakpoint family, members of which have been observed to be overexpressed in sarcomas and non-small-cell lung cancer." (PMID 29654271, 2018). "Loss of heterozygosity (LOH) for the 1p36 locus encompassing the NBPF1 gene has been shown in neuroblastoma and some other tumors." (PMID 24098321, 2013). "The expression level of NBPF1, determined for a panel of 32 neuroblastoma cell lines, varied widely between the different samples, like it did in the expression analysis of the total NBPF family." (PMID 18493581, 2008). "Alternatively, as our NBPF1 expression profiling revealed a decreased expression in neuroblastoma cell lines with a heterozygous deletion of the NBPF1 locus, it is also possible that NBPF1 acts as a haploinsufficient gene." (PMID 18493581, 2008). "Though it is located outside of the smallest region of overlap defined by a large-scale analysis of neuroblastoma tumors, at least one copy of the region encompassing the NBPF1 gene is deleted in most neuroblastomas with 1p deletion." (PMID 18493581, 2008). "These amplicons were analyzed in a panel of 31 neuroblastoma cell lines, some with a heterozygous deletion of NBPF1 (n = 25) and some with two copies of the NBPF1 gene (n = 5)." (PMID 18493581, 2008). "The NBPF was originally identified by the disruption of NBPF1 in a neuroblastoma patient, and so it may play a role in neuroblastoma and other cancers." (PMID 40564862, 2025).
neuroblastoma (continued). "Therefore, disruption of the NBPF1 gene in neuroblastoma patients, and possibly in other cancers as well, can result in several dysregulations of cellular activity and thereby contribute to the initiation or progression of cancer." (PMID 25958384, 2015). "This decreased expression is a hallmark of tumor suppression activity, which motivated us to investigate whether NBPF1 overexpression arrests the cell cycle also in neuroblastoma cell lines." (PMID 25958384, 2015). "The second was with the neuroblastoma breakpoint family member 1 (NBPF-1), a pseudogene that functions as a tumor suppressor for neuroblastomas." (PMID 37834296, 2023). "The disruption of both NBPF1 and ACCN1 genes in this neuroblastoma patient indicates that these genes might suppress development of neuroblastoma and possibly other tumor types." (PMID 18493581, 2008).
cervical cancer (5 papers, 2017 to 2023). A primary or metastatic malignant neoplasm involving the cervix. "Functional studies in cervical cancer cell lines identified NBPF1 regulation of cell invasion and apoptosis by activating PI3K/mTOR signaling pathways, which are key mechanisms in cancer progression." (PMID 37454130, 2023). "Neuroblastoma breakpoint family member 1 (NBPF1) inhibits cervical cancer invasion via regulating the PI3K/mTOR signaling pathway." (PMID 30333561, 2018).
colorectal cancer (5 papers, 2008 to 2023). A primary or metastatic malignant neoplasm that affects the colon or rectum. "Among the mutated genes in the adenomatous tissue samples involved in our study, PCDHGB4, AHRR, KIF4, LPAR6, NBPF1, and NCEH1 were already associated with colorectal cancer formation, while ANKRD30A, ITIH1, and KIAA0556 were related to other types of cancers." (PMID 36765865, 2023). "DLD1 cells, a colorectal cancer cell line, with increased NBPF1 expression had a decrease of clonal growth by a soft agar assay." (PMID 31956350, 2020).
colon cancer (3 papers, 2008 to 2025). "LC-MS/MS analysis was used to investigate the proteome of DLD1 colon cancer cells with induced NBPF1 expression." (PMID 25958384, 2015). "Moreover, NBPF1-expressing colon cancer cells formed significantly fewer colonies in soft agar than control cell lines, indicating that NBPF1 might be important for suppression of anchorage-independent growth." (PMID 25958384, 2015). "Furthermore, expression of NBPF1 in a human colorectal cell line severely suppressed soft agar colony formation, demonstrating that NBPF1 might act as a TSG, at least in colon cancer." (PMID 18493581, 2008). "We could not confirm NBPF1-dependent CDKN1A upregulation in DLD1Tr21/NBPF1 colon cancer cells." (PMID 25958384, 2015).
prostate carcinoma (3 papers, 2015 to 2023). A carcinoma that arises from epithelial cells of the prostate gland. "Moreover, NBPF1 induction decreased the expression of S100P, the expression of which is associated with drug resistance, metastasis, and poor clinical outcome in many different cancers such as colon, breast and prostate cancer." (PMID 25958384, 2015).
adenoma (1 paper, 2023). A neoplasm arising from the epithelium. "Interestingly, NBPF1—mutated in 2/27 of our adenoma samples—is a cancer driver gene in CRC as a tumor suppressor and also a potential regulator and biomarker for CRC." (PMID 36765865, 2023).
adrenocortical carcinoma (1 paper, 2022). "In particular, compared to other tumor types, there was a strong negative correlation between NBPF1 expression and various components of the tumor microenvironment in adrenocortical carcinoma (ACC)." (PMID 36060966, 2022).
breast carcinoma (1 paper, 2023). "Additional studies to characterize NBPF1 function and recurrent mutations in breast cancer are warranted." (PMID 37454130, 2023). "The role of NBPF1 in breast cancer is still unknown, though it is reported that NBPF1 mutations in noncoding regulatory regions are higher in breast cancer patients, along with hypermethylation." (PMID 37454130, 2023).
cholangiocarcinoma (1 paper, 2022). A carcinoma that arises from the intrahepatic biliary tree (intrahepatic cholangiocarcinoma) or from the junction, or adjacent to the junction, of the right and left hepatic ducts (hilar cholangiocarcinoma). "Subsequently, we further investigated NBPF1 alterations using the cBioPortal database and observed that NBPF1 showed the greatest prevalence of copy number alterations in patients with cholangiocarcinoma." (PMID 36060966, 2022). "Given the probable role of NBPF family genes in pathological processes, it is worth examining the role of NBPF1 gene variation, particularly copy number alterations, as a cancer sensor in patients with cholangiocarcinoma." (PMID 36060966, 2022).
cystic teratomas of the ovary (1 paper, 2022). "Among the 15 prevalent mutated genes, 8 with different variants in exons with changes in protein coding are important for the development of mature cystic teratomas of the ovary: FLG, MUC17, MUC5B, RP1L1, NBPF1, SLC29A3, SGK223, and FAM186A." (PMID 36289533, 2022).
hepatocellular carcinoma (1 paper, 2023). A malignant tumor that arises from hepatocytes. "On the other hand, it has been shown that NBPF1 regulates colony formation and the invasion of hepatocellular carcinoma cells, thus acting as an oncogene." (PMID 37296706, 2023).
liver cancer (1 paper, 2022). An epithelial or non-epithelial malignant neoplasm that arises from the liver. "On the other hand, there is evidence that NBPF1 regulates the colony formation, invasion, and maintenance of liver cancer cells and hence functions as an oncogene." (PMID 36060966, 2022).
lymphoma (1 paper, 2024). A malignant (clonal) proliferation of B- lymphocytes or T- lymphocytes which involves the lymph nodes, bone marrow and/or extranodal sites. "NBPF1 was the most frequently mutated gene in our cohort; however, all the detected variants, albeit confirmed somatic, are frequent polymorphisms in the healthy population (MAF > 1%), suggesting that they likely represent passenger variants with no role in the biology of the lymphoma." (PMID 39478125, 2024).
thyroid cancer (1 paper, 2022). "We found that, compared with the corresponding normal tissue, NBPF1 was differentially expressed in colorectal, endometrial, liver, renal, stomach, and thyroid cancers." (PMID 36060966, 2022).
tumor (16 papers, 2008 to 2025). "Our results show that NBPF1 is variably expressed in distinct tumor tissues and is also closely linked to clinical outcomes." (PMID 36060966, 2022). "We further explored the possible molecular mechanisms of action of NBPF1 in tumorigenesis and progression by analyzing the association between NBPF1 and tumor immunity in various cancers." (PMID 36060966, 2022). "Given the association between NBPF1 and tumor immunity, we explored the role of NBPF1 in tumor immunotherapy." (PMID 36060966, 2022). "We discovered that NBPF1 expression differed among tumor tissues and was linked to clinical outcomes across different cancers." (PMID 36060966, 2022). "Particularly in patients with ACC, NBPF1 and related immune risk genes may impact tumorigenesis, the tumor microenvironment, and anti-tumor drug selection." (PMID 36060966, 2022). "In this paper, bioinformatics techniques were employed to analyze NBPF1 expression across different cancers and investigate the relationship between NBPF1 and clinical features, prognosis, genetic alteration, and tumor immune microenvironment, respectively." (PMID 36060966, 2022). "Considering the impact of different pathological stages on the tumor microenvironment, we compared the level of immune cell infiltration between the high- and low-NBPF1 expression groups in patients with ACC with early- (N0) and late-stage (N1) tumors." (PMID 36060966, 2022). "We further analyzed the correlation between NBPF1 transcription and tumor-infiltrating lymphocytes (TIL) abundance using the TISIDB database." (PMID 36060966, 2022). "Our study employed publicly financed cancer genomics programs and archives to decipher the landscape of various tumor types based on NBPF1 expression to determine its likely function in tumorigenesis." (PMID 36060966, 2022). "Although identified in a single study series in this review, NBPF1 has tumor growth inhibitory effects through the inhibition of the PI3K signaling pathway." (PMID 34209172, 2021). "We have shown that NBPF1 can act as a tumor suppressor by inhibiting the cell cycle, by cell death induction or by expression modulation of various proteins implicated in cancer." (PMID 25958384, 2015). "All genes located distal to the NBPF1 gene would therefore show LOH in the tumor, including a number of recently identified TSGs located in this region." (PMID 18493581, 2008). "NBPF1 is known to deactivate the PI3K signaling pathway leading to tumor growth inhibition." (PMID 35008677, 2021). "We also report for the first time that two CRC driver gene, FCGBP and NBPF1 might function as tumor suppressors and prognostic markers for CRC." (PMID 31956350, 2020). "Considering this genetic defect and the frequent genomic alterations of the NBPF1 locus in several cancer types, we hypothesized that NBPF1 is a tumor suppressor." (PMID 25958384, 2015). "This demonstrates that NBPF1 exerts cell-specific tumor suppressive effects." (PMID 25958384, 2015). "We previously reported evidence for a tumor suppressor role of NBPF1." (PMID 25958384, 2015). "In conclusion, this study advances the understanding of the role of NBPF1 as a tumor suppressor." (PMID 25958384, 2015). "In any case, these data indicate that the proposed tumor suppressive properties of NBPF1 might be very versatile and cell-specific." (PMID 25958384, 2015). "Given the intricacy of the mechanisms underlying the anti-cancer immune response, we assessed immune activation processes and immune infiltration among 33 cancer types and found that NBPF1 may inhibit the activation of anti-tumor immunity, particularly in ACC and SARC." (PMID 36060966, 2022). "Based on these findings, we hypothesized that NBPF1 acts as a tumor suppressor." (PMID 25958384, 2015). "We found 5 of these CARs/lincRNAs (MALAT1, MEG3, NEAT1, NBPF1, and AC058791.1) significantly downregulated in primary tumor samples compared to normal tissue." (PMID 25264628, 2014).
tumor (continued). "Therefore, we propose that NBPF1 may work in BRCA and LUAD patients by modulating the number of anti-tumor mast cells in the tumor microenvironment, which further contributes to a better prognosis." (PMID 36060966, 2022).
cancer (9 papers, 2008 to 2025). A tumor composed of atypical neoplastic, often pleomorphic cells that invade other tissues. "This heterogeneity may reflect different underlying functions and mechanisms of NBPF1 across multiple cancer types." (PMID 36060966, 2022). "A pan-cancer study obtained the information that NBPF1 is differentially expressed in a variety of cancers including RCC." (PMID 37296706, 2023). "In our study, the expression of NBPF1 was significantly downregulated in 10 cancer types in TCGA, while others showed higher expression when compared with paired adjacent normal tissues." (PMID 36060966, 2022). "Based on the typical expression values of NBPF1 in 33 types of cancer, patients were separated by median into NBPF1-high and NBPF1-low transcription groups." (PMID 36060966, 2022). "We observed different trends of up and downregulation of NBPF1 expression in different immune subtypes of a given cancer type, suggesting the potential immunological role of NBPF1 in certain tumors." (PMID 36060966, 2022). "This comprehensive pan-cancer study revealed the probable biological function of NBPF1 in the development, progression, and clinical prognosis of various human cancers." (PMID 36060966, 2022). "The IPA analysis also grouped the genes that were differentially expressed upon NBPF1 expression into a number of biological mechanisms related to dermatological disease, inflammatory disease, inflammatory response, cancer, and endocrine system disorders." (PMID 25958384, 2015). "We observed the genetic alteration status of NBPF1 in 33 types of cancer in the TCGA cohort." (PMID 36060966, 2022). "Additionally, there were discrepancies in the expression levels of NBPF1 in diverse cancer subtypes." (PMID 36060966, 2022). "Interestingly, we found that in a small subset of cancer types, high expression of NBPF1 leads to worse survival outcomes." (PMID 36060966, 2022). "Thus, high levels of NBPF1 expression may predict unsatisfactory immunotherapeutic outcomes when targeting immune checkpoint genes in these cancers." (PMID 36060966, 2022). "In addition to multilevel data comparison of NBPF1 across multiple cancers, we examined the links between NBPF1 expression and clinical manifestations, prognosis, TIME, TMB, immunotherapeutic effectiveness, genetic alteration, function labeling, and enrichment." (PMID 36060966, 2022). "Interestingly, NBPF1 was negatively associated with most immune cells in 30 cancer types, except for KIHC and PAAD, with the negative correlation being particularly evident in ACC." (PMID 36060966, 2022). "Moreover, we demonstrated that NBPF1 expression in ACC and SARC was adversely associated with the recruitment of immune cells involved in the anti-cancer immune response, and the seven steps of the anti-cancer immune response were differentially suppressed in patients with high expression of NBPF1." (PMID 36060966, 2022). "The region contains multiple genes with a known or suspected role in cancer including ARID1A, E2F2, NBPF1, PAX7, RUNX3 and SDHB." (PMID 25420937, 2014). "First, we used the TIMER database to ascertain the mRNA expression of NBPF1 in multiple cancers and corresponding noncancerous tissues, which revealed that NBPF1 was differentially expressed in various cancers." (PMID 36060966, 2022). "Furthermore, a strong negative correlation was found between NBPF1 transcription and DNA methylation in 14 types of cancers, and we also observed that patients with ACC with higher DNA methylation of NBPF1 showed a better prognosis in PFS." (PMID 36060966, 2022).
cancer (continued). "Additionally, NBPF1 was found to be negatively correlated with numerous immunomodulators (MHC, chemokines, receptors, and immunostimulators) in ACC, SARC, and THCA, which are crucial for the activities of the cancer immunity cycle." (PMID 36060966, 2022). "However, a systematic pan-cancer analysis has thus far not been undertaken, and the significance of NBPF1 in the occurrence and progression of many malignancies is uncertain." (PMID 36060966, 2022).
NBPF1 also shares sentences with these, for which no sentence is quoted: cutaneous squamous cell carcinoma (2 papers); endocrine system disorder (1); gastric cancer (1); infection (1); non-small cell lung carcinoma (1); pancreatic adenocarcinoma (1); primary immunodeficiency (1); sarcoma (1).